ATP7A (ATPase copper transporting alpha)
Diseases named in the same sentence as ATP7A in open-access papers (continued):
Sharing a sentence is not in itself a finding about the gene and the disease.
cancer (continued). "For instance, cancer cells were found to be more sensitive to THINYL ESTRADIOL and Estramustine with the increased expression of ATP7A genes, while they were insensitive to Dasatinib." (PMID 37464443, 2023). "The existing literature has not confirmed the direct relationship between FDX1 and NLRP3, but researchers suggested that ATP7A and NLRP3 are negatively correlated in pan-cancer." (PMID 37138870, 2023). "Despite the fact that CTR1, ATOX1, ATP7A, and ATP7B are involved in cisplatin transportation, as previously stated, they are also involved in copper uptake, distribution, and efflux in cancer." (PMID 37049685, 2023). "The overexpression of ATP7A or ATP7B can lead to intracellular copper accumulation and cell death with aging-related diseases and various cancers." (PMID 38159257, 2023). "In contrast, eight regulators (PDHA1, ATP7A, LIPT1, LIPT2, GLS, ATP7B, GCSH, and CDKN2A) were upregulated in cancer tissues." (PMID 36672336, 2023). "Although existing literature reports indicate that ATP7A and ATP7B, are critical for the cisplatin resistance of cancers." (PMID 34298686, 2021). "On the other hand, ATP7A, a copper transporting P-type ATPase, has been also implied in CDDP resistance in cancer by inducing the efflux of platinum drugs." (PMID 31990955, 2020). "In this meta-analysis, we systematically evaluated the relationship between four copper transporters (CTR1, CTR2, ATP7A and ATP7B) that influence cellular platinum accumulation and prognosis of cancer patients who received chemotherapy." (PMID 27980217, 2017). "The influence of copper transporters on the import (CTR1) and efflux of cisplatin (ATP7A and/or ATP7B) has been observed in a variety of human cancer cell lines." (PMID 23613873, 2013). "Cancer cells can develop resistance to cisplatin by decreasing the concentration by reducing its inflow through CRT1 (human creatine transporter 1) copper transporters and increasing its outflow through ATP7A (copper transporter P-type ATPase) transporters." (PMID 40869430, 2025). "Recent studies suggest that the expression levels of Cu‐ATPases, particularly ATP7A and ATP7B, may be related to the occurrence and progression of cancer." (PMID 39267265, 2024). "As to the genes of copper death, ATP7A is positively related to 29 cancers, while LIAS is negatively related to 13 tumors." (PMID 37671947, 2023). "Copper efflux proteins, ATP7A and ATP7B, are also involved in cancer progression." (PMID 36296659, 2022). "While many mechanisms have been proposed for Pt-drug transport, the high-affinity copper transporter (hCtr1), Cu chaperone (Atox1), and Cu exporters (ATP7A and ATP7B) are also involved in cDDP transport, highlighting Cu homeostasis regulation in Pt-based cancer therapy." (PMID 34201235, 2021). "It is also possible that Cu might enhance either expression or efficacy of the organic cationic transporters (ATP7A and ATP7B) in some unknown way that might facilitate the drug influx in the cancer cells." (PMID 30941331, 2019). "Our findings provide evidence that decreased drug efflux by knockdown ATP7A in CRC cells could lead up to higher tissue distribution and intracellular drug accumulation to form destructive DNA-platinum adducts which ultimately destroy cancer cells." (PMID 35265524, 2022). "Some key regulatory genes and proteins were modulated, such as ATP7A, ABCG2, ABCC1 and ABCB1 in response to EC-synthetic retinoids, suggesting that their expression may be under the regulation of retinoid signaling pathways with a potential role in diminishing cancer resistance and carcinogenesis." (PMID 36012706, 2022).
infection (22 papers, 2012 to 2025). The state of being infected such as from the introduction of a foreign agent such as serum, vaccine, antigenic substance or organism. "In this sense, A. fumigatus had an increased survival during infection in ATP7a-deficient zebrafish." (PMID 32849434, 2020). "Deletion of ATP7a in murine models resulted in severe growth defects and premature death, making investigation into susceptibility to infection difficult." (PMID 24364001, 2013). "Furthermore, mice with a myeloid-specific knockout of ATP7A, the copper ATPase that pumps toxic copper ions into the macrophage phagosome, are more susceptible to infection with Salmonella Typhimurium." (PMID 32117089, 2020). "constructed Atp7aLysMcre mice, a myeloid-specific ATP7A knockout model, revealing that a higher percentage of S. Typhimurium recovered in Atp7aLysMcre macrophages within 2 hours after infection." (PMID 38106478, 2023). "In order to control the infection of M. tuberculosis, host macrophages utilize ATP7A to pump copper into phagosomes, conducting a copper nutritional immunity." (PMID 38106478, 2023). "For example, the copper importer CTR1 is upregulated in macrophages during infection, followed by copper-stimulated trafficking of ATP7A from the Golgi to the phagolysosome." (PMID 35089085, 2022). "Phagocytic cell Cu levels have been shown to increase in response to infection, with Cu delivered to the phagolysosome via the Cu(I)-transporter ATP7A." (PMID 36413018, 2022). "infection, macrophage deploys the Cu-ATPase, ATP7A, to exert Cu-mediated toxicity over the pathogen." (PMID 34958799, 2022). "Infection based studies suggest that macrophages elevate copper levels inside the phagosome by locating the P-type copper ATPase pump (ATP7a) to the phagosome membrane." (PMID 32849434, 2020). "Aspergillus fumigatus conidia infection of alveolar macrophages increases ATP7A expression consistent with elevation of phagosomal copper as an initial phagocyte response." (PMID 30452484, 2018). "Besides, S. Typhimurium triggered copper accumulation at ‘copper hot spots’ in bone-marrow-derived macrophages (BMM) via upregulating Atp7a gene 10 to 15 folds at 14 h post-infection." (PMID 38106478, 2023). "Infection with S. enterica and M. tuberculosis leads to an upregulation of ATP7A." (PMID 38106478, 2023). "Previous infection studies suggested that macrophages elicit oxidative stress in the pathogens and, concomitantly, also accumulated Cu2+ ions inside microbe-containing phagosomes via the upregulation of Ctr1 and the P-type copper ATPase ATP7A." (PMID 34356919, 2021). "The attenuation of the ΔcopA mutant during infection may be partially explained by the activity of the ATP7a copper transporter expressed in macrophages and other cells because this strain is unable to export copper." (PMID 24364001, 2013). "In response to infection, aquaporin (AQP11) expression was reduced, whereas ATPase transporters (ATP2A2, ATP7A) expression were significantly elevated." (PMID 39703373, 2024). "Therefore, we compared renal ceruloplasmin, CTR1, ATP7A and ATP7B protein levels in animals at different stages of infection." (PMID 27362522, 2016).
genetic disorders (9 papers, 2012 to 2025). "Genetic disorders of ATP7B cause excess Cu and trigger the pathogenesis of Wilson disease, whereas genetic disorders of ATP7A cause Cu deficiency in Menkes disease." (PMID 39062487, 2024). "This enables zinc to bind excess copper, which avoids genetic disorders and releases oncogenic enzymes, such as ATP7A, ATP7B, CTR1, and ATOX1, to regulate homeostasis." (PMID 37049685, 2023). "Genetic diseases are caused by impaired Cu transporters CTR1, ATP7A, or ATP7B but little is known about the regulatory mechanisms by which these proteins meet the fluctuating demands of Cu in specific tissues." (PMID 37391383, 2023). "In terms of treatability, TSC1-, TSC2-, SLC35A2-, ATP7A-, ALDH7A1-, and MMACHC-related disorders had specific therapeutic regimens and accounted for 18.5% (19/103) of the cases with genetic disorders." (PMID 35330882, 2022).
neurodegenerative disease (5 papers, 2020 to 2025). A disorder of the central nervous system characterized by gradual and progressive loss of neural tissue and neurologic function. "Considering various factors including genetic mode, mutation type, allele frequency, and published literature, it is acceptable that ATP7A M1311V has high functional impact on neurodegenerative disease." (PMID 31959876, 2020). "Furthermore, dHMNX-derived motor neurons can be added to the list of in vitro cellular models that serve as a tool to study common mechanisms of pathogenesis for inherited peripheral neuropathies and the importance that ATP7A and Cu-dependent pathways have in other neurodegenerative diseases." (PMID 31969342, 2020).
metabolic disease (3 papers, 2021 to 2024). A congenital disorder (due to inherited enzyme abnormality) or acquired (due to failure of a metabolically important organ) disorder resulting from an abnormal metabolic process. "Others have found that ATP7A in adipose tissues has a nonnegligible role in the regulation of aging-related metabolic disease and whole-body fat homeostasis." (PMID 37143115, 2023).
neurodevelopmental disorder (3 papers, 2017 to 2021). A behavioral and cognitive disorder with onset during the developmental period that involves impaired or aberrant development of intellectual, motor, or social functions. "The ATP7A interactome concentrated gene products implicated in neurodegeneration and neurodevelopmental disorders, including subunits of the Golgi-localized conserved oligomeric Golgi (COG) complex." (PMID 28355134, 2017). "Here, we defined the ATP7A interactome which was enriched in products implicated in neurodegeneration and neurodevelopmental disorders, including the conserved oligomeric Golgi (COG) complex." (PMID 28355134, 2017). "We prioritized for confirmation ATP7A interactome candidates due to their association with neurodegenerative and neurodevelopmental disorders." (PMID 28355134, 2017). "These analyses indicate that the ATP7A interactome enriches gene products previously implicated in neurodegenerative and neurodevelopmental disorders, suggesting that these associations could participate in the neuropathogenesis of ATP7A genetic deficiencies." (PMID 28355134, 2017).
ATP7A also shares sentences with these, for which no sentence is quoted: tauopathy (12 papers); Cognitive impairment (5); developmental delay (5); neurological disorder (5); breast tumor (4); epilepsy (4); motor neuron disease (4); spinal muscular atrophy (4); Arthritis (3); Ataxia (3); disc degeneration (3); MEDNIK syndrome (3); rheumatoid arthritis (3); X-linked disease (3); aceruloplasminemia (2); connective tissue disorder (2); dementia (2); leukemia (2); metabolic syndrome (2); osteoarthritis (2); peripheral neuropathies (2); Adult onset (1); allergic rhinitis (1); amyloid (1); Anxiety (1); asthma (1); Atrophy (1); autism spectrum disorder (1); autoimmune disorders (1); bacterial infection (1).
A further 68 diseases each share a sentence with ATP7A in 1 paper.